CX3CR1 (C-X3-C motif chemokine receptor 1)
Diseases named in the same sentence as CX3CR1 in open-access papers (continued):
Sharing a sentence is not in itself a finding about the gene and the disease.
Gastric tumors (2 papers, 2020 to 2022). "Gastric tumors exhibit increased CX3CL1 expression, and CX3CR1 is highly expressed in association with more advanced stages." (PMID 32432034, 2020). "Cell sorting of gastric tumours revealed that IL-33 chiefly localized to gastric (tumour) epithelial cells and was absent from tumour-infiltrating immune cells (except modest IL-33 enrichment within CD11b+ CX3CR1+CD64+MHCII+ macrophages)." (PMID 35677533, 2022).
Granuloma (2 papers, 2014 to 2015). A compact, organized collection of mature mononuclear phagocytes, which may be but is not necessarily accompanied by accessory features such as necrosis. "Here, we describe studies in Cx3cr1−/− mice and demonstrate the role of Cx3cr1 in the pathoetiology of granuloma formation during acute schistosomiasis." (PMID 26035381, 2015). "Highlighted Article: A reduction in CX3CR1 signaling provides protection for mice against pro-inflammatory responses and hepatic granuloma formation during acute schistosomiasis." (PMID 26035381, 2015). "Using confocal microscopy, we observed that CX3CR1-GFP+ cells with extended processes and macrophage-like morphology are found within granulomas at various stages of granuloma formation." (PMID 24967715, 2014). "Flow cytometric analysis of liver leukocytes showed an increase in the frequency of both Ly6Chigh and Ly6Clow CX3CR1-GFP+ monocytes in infected mice at 6 and 7 weeks, which coincides with the formation of granulomas in the liver." (PMID 24967715, 2014). "Differential labeling of CX3CR1-GFP+ cells in the blood and the tissue showed CD4+ T cell dependent accumulation of PD-L2+ CX3CR1-GFP+ AAM in the tissues as granulomas form." (PMID 24967715, 2014). "In both uninfected mice and infected mice that do not yet have established granulomas (5 weeks post-infection), 80–90% of the CX3CR1-GFP+ cells were CD45+ and only 10–20% are CD45−, indicating that they are mostly intravascular when granulomas are not present." (PMID 24967715, 2014). "Intravital imaging of CX3CR1-GFP+ Ly6Clow monocytes revealed alterations in patrolling behavior including arrest around eggs that were not encased in granulomas." (PMID 24967715, 2014). "In small granulomas, CX3CR1-GFP+ cells are directly in contact with the eggs (left most panels), but within larger granulomas the CX3CR1-GFP+ cells are found in the fringes of the granuloma (second to rightmost panels), or dispersed throughout the liver (rightmost panels)." (PMID 24967715, 2014). "However, patrolling behavior around eggs in fully developed granulomas was not altered, suggesting that CX3CR1-GFP+ crawling monocytes respond to eggs when they are in the blood, but not when they are encased in granulomas." (PMID 24967715, 2014).
Hematuria (2 papers, 2019 to 2022). The presence of blood in the urine. "This was followed by migration of CX3CR1+ cells to the kidneys through blood circulation, resulting in the development of hematuria caused by glomerular vascular injury." (PMID 35054911, 2022). "CX3CR1-positive Tc cells are more frequent not only in the blood of IgAN patients with hematuria, but also in tonsils of IgAN patients." (PMID 30406499, 2019).
Hip dysplasia (2 papers, 2022 to 2024). The presence of developmental dysplasia of the hip. "Several chromosomal loci that are closely associated with unilateral or bilateral hip dysplasia, such as CX3CR1, GDF5, and HOX, were identified through familial aggregation studies of multiple DDH patients." (PMID 39156961, 2024). "Among other studies that utilized DigiGait in a mutant mouse model, a shortened stance time was observed in mice lacking CX3CR1 resulting in phenotypic hip dysplasia." (PMID 35457064, 2022).
Huntington disease (2 papers, 2022 to 2023). Huntington disease (HD) is a rare neurodegenerative disorder of the central nervous system characterized by unwanted choreatic movements, behavioral and psychiatric disturbances and dementia. "While dark microglia were previously reported at adulthood in several mouse models of pathology (e.g., prenatal and maternal immune activation, middle-aged APP-PS1, chronic stress, CX3CR1 knockout, R6/2 model of Huntington’s disease;), their presence in the human brain had yet to be reported." (PMID 36167544, 2022).
Hyperinsulinemia (2 papers, 2021 to 2022). An increased concentration of insulin in the blood. "More evidence supports that initial increase of insulin secretion by CX3CL1/CX3CR1 may be just a defensive reaction to inflammation, which can lead to chronic hyperinsulinemia and depletion of functional reserves of β-cells." (PMID 35370759, 2022). "Additionally, studies have shown that high CX3CL1 levels can lead to depletion of functional reserves of β cells and chronic hyperinsulinemia, while inhibition of CX3CL1/CX3CR1 system can regulate pancreatic islet β-cell function." (PMID 34054797, 2021).
Hypoglycemia (2 papers, 2019). A decreased concentration of glucose in the blood. "To further explore the activation state of monocytes after hypoglycemia, we studied expression levels of chemokine receptor CX3CR1 and integrin CD11b." (PMID 30252067, 2019). "Confocal imaging of triple fluorescent labeled material in fasted, insulin-injected CX3CR1+/gfp mice (microglia reporter strain on C57BL/6 background) revealed close apposition of microglia and hypoglycemia-activated, c-FOS positive neurons." (PMID 30996341, 2019). "Indeed, CX3CR1−/− mice with impaired neuron-to-microglia communication did not display overt microglia activation and did not develop hypoglycemia in response to insulin challenge." (PMID 30996341, 2019).
interstitial lung disease (2 papers, 2012 to 2024). A diverse group of lung diseases that affect the lung parenchyma. "In this study, we retrospectively analyzed the expressions of CX3CL1/fractalkine and its corresponding receptor, CX3CR1, in muscle and lung with interstitial lung disease (ILD) of PM patients and DM patients, and determined the correlation between serum soluble CX3CL1 level and disease activity." (PMID 22394569, 2012). "The CX3CL1/CX3CR1 axis has also been associated with driving a proinflammatory phenotype in disease settings, and administration of an anti-CX3CL1–neutralizing antibody in a model of interstitial lung disease resulted in a decrease of an M1-described inflammatory macrophage infiltration." (PMID 38618956, 2024).
kidney inflammation (2 papers, 2023 to 2025). "Investigations suggest that the gut microbial dysbiosis causing a leaky gut activates CX3CR1-expressing cells, which subsequently increase inflammation, thus causing aggregated spleen and/or kidney inflammation." (PMID 38299151, 2023). "Here, we determined that CX3CL1 expression in mesangial cells and CX3CR1+ monocyte/macrophage infiltration in glomerulus was up-regulated and was associated with glomerulus regional immune injury in clinical specimen and anti-Thy1 nephritis." (PMID 40458609, 2025). "We established anti-Thy1 nephritis and blocked the infiltration of CX3CR1+ monocytes/macrophages into injured glomerulus by injecting AZD8797-CX3CR1 antagonist." (PMID 40458609, 2025). "The anti-Thy1 nephritis model was established as the MsPGN model to determine the regulation of CX3CL1 and CX3CR1 during the development of disease." (PMID 40458609, 2025).
latent infection (2 papers, 2025). "In contrast, US28, a virally encoded G protein-coupled receptor (GPCR) homologous to CX3CR1 can be expressed on the surface of latently infected cells and is essential for the maintenance of latent infection." (PMID 40872232, 2025). "MIs are recruited as CX3CR1+CD8+ T cells by CX3CL1, which is released from inflamed blood vessels, to sites of latent infection and expand on non-hematopoietic cells in IL-15-rich niches." (PMID 40028277, 2025).
lung squamous cell carcinoma (2 papers, 2021 to 2023). "LAML (Acute Myeloid Leukemia) and LUSC (lung squamous cell carcinoma) patient samples with high CX3CR1 expression had significantly worse overall survival and relapse free survival than those with low CX3CR1 expression." (PMID 37771579, 2023).
lymphoma (2 papers, 2017 to 2022). A malignant (clonal) proliferation of B- lymphocytes or T- lymphocytes which involves the lymph nodes, bone marrow and/or extranodal sites. "The chemokine receptor expression profiles of de novo DLBCL and tFL substantially differed from those of GC-B, with at least 5-fold higher expression of 15 out of the 18 investigated chemokine receptors (CCR1–CCR9, CXCR1, CXCR2, CXCR6, CXCR7, CX3CR1 and XCR1) in these lymphoma subtypes." (PMID 35887224, 2022).
memory impairment (2 papers, 2023). "However, our findings confirmed that CX3CR1 deficiency had a protective effect on HH-induced memory impairment." (PMID 37234914, 2023). "CX3CR1 knock out and wide type mice were exposed to a simulated plateau at 7000 m for 48 h to construct the model of hypobaric hypoxia-induced memory impairment." (PMID 37234914, 2023). "The current study investigated the mechanism of the CX3CL1/CX3CR1 signal in memory impairment in mice induced by simulated high-altitude exposure." (PMID 37234914, 2023). "On the other hand, Aβ administration leads to an increase in CX3CR1 levels When the CX3CR1 expression is diminished, Aβ-induced microglial activation, synaptic plasticity blockade, and memory impairment are also reduced." (PMID 36644710, 2023).
migraine (2 papers, 2013 to 2022). "Compared with that in the sham group, the expression of CX3CR1/FKN in the sp5c was increased in the migraine group and further increased in the comorbidity group (FCX3CR1 = 21.29, P < 0.001; FFKN = 24.12, P < 0.001)." (PMID 35382731, 2022). "Compared to those in the sham group, CX3CR1 and iba1 immunoactivities were considerably higher in the migraine group and even higher in the comorbidity group." (PMID 35382731, 2022). "We next explored the protein expression of CX3CR1/FKN/proBDNF/BDNF to examine the effects of AZD8797 on migraine model rats after seizures at the molecular level." (PMID 35382731, 2022). "We also demonstrated that BDNF expression was regulated by the FKN/CX3CR1 axis in migraine model rats." (PMID 35382731, 2022). "Future studies are needed to illustrate the feasibility of targeting the FKN/CX3CR1 axis in migraine patients, especially in female patients." (PMID 35382731, 2022). "Moreover, SE-induced increases in nociceptive behaviour and FKN/CX3CR1 axis expression in migraine model rats." (PMID 35382731, 2022). "AZD8797 (a CX3CR1 inhibitor) prevented the worsening of hyperalgesia and microglial activation in migraine model rats after seizures, while FKN infusion in migraine model rats exacerbated hyperalgesia and microglial activation associated with BDNF-Trkb signalling." (PMID 35382731, 2022). "Then, we assessed FKN/CX3CR1 expression in the migraine and comorbidity groups." (PMID 35382731, 2022). "Although there have been few studies on the FKN/CX3CR1 axis in migraine, published research suggests that CX3CR1 may be involved in the occurrence of migraine." (PMID 35382731, 2022). "To further investigate whether seizures facilitate migraines through the FKN/CX3CR1 axis, we injected FKN into the sp5c of migraine model rats using stereotactic brain injection, and the sham groups received the same amount of PBS." (PMID 35382731, 2022). "Furthermore, we explored whether the FKN/CX3CR1 axis intervention regulated nociceptive behaviour in migraine model rats, further revealing its role in migraine." (PMID 35382731, 2022). "In line with this hypothesis, our study supports this idea by showing that neurons activate microglia in the cortex/thalamic/sp5c via the FKN/CX3CR1 axis, which leads to enhanced BDNF production in migraine model rats following an epileptic episode." (PMID 35382731, 2022).
Miscarriage (2 papers, 2018 to 2021). A pregnancy that ends at a stage in which the fetus is incapable of surviving on its own, defined as the spontaneous loss of a fetus before the 22th week of pregnancy. "The additional characterization of the macrophage polarization status using the M1 polarization markers TLR2 and iNOS and the M2 polarization markers CCL1 and CX3CR1 confirmed the loss of M2 polarized marcrophages in recurrent miscarriages." (PMID 29949879, 2018).
Myositis (2 papers, 2012 to 2020). "Our data indicate that the timing of monocyte recruitment to the site of inflammation in RRV-induced myositis is critical for the subsequent accumulation of M2-like CX3CR1+ MP during recovery." (PMID 32127460, 2020). "CX3CR1+ macrophages are important for tissue repair in RRV-induced myositis." (PMID 32127460, 2020). "Here, we show that myositis induced by Ross River virus (RRV) infection is driven by CD11bhi Ly6Chi inflammatory monocytes and followed by the establishment of a CD11bhi Ly6Clo CX3CR1+ macrophage population in the muscle upon recovery." (PMID 32127460, 2020). "Our earlier data showed that CX3CL1 and CX3CR1 were expressed in murine EAM and that inhibition of CX3CL1 ameliorated myositis." (PMID 22394569, 2012).
neovascular age-related macular degeneration (2 papers, 2023 to 2025). "Ethnic differences in CX3CR1-related disease susceptibility were also highlighted in an Algerian population, where the T280M was associated with an increased risk of neovascular age-related macular degeneration, whereas no such association was observed in Greek or Indian populations." (PMID 40733585, 2025).
Pain (2 papers, 2016 to 2024). An unpleasant sensory and emotional experience associated with actual or potential tissue damage, or described in terms of such damage. "Therefore, we were able to control the ablation of CX3CR1+ cells by diphtheria toxin (DT) application and directly investigated the temporal role of CX3CR1+ cells in chronic pain behaviours after L4 SNT, a well-established mouse model of neuropathic pain." (PMID 27349690, 2016).
primary biliary cholangitis (2 papers, 2016 to 2020). Primary biliary cholangitis (PBC) is a chronic and slowly progressive cholestatic liver disease of autoimmune etiology characterized by injury of the intrahepatic bile ducts that may eventually lead to liver failure. "This contribution to liver injury has also been shown in primary biliary cirrhosis where fractalkine triggers the infiltration of CX3CR1 expressing immune cells to the liver that promote inflammation." (PMID 27561705, 2016). "Moreover, CX3CL1/CX3CR1 signaling triggers a rapid mobilization and accumulation of immune cells to the sites of injury and is involved in several inflammatory diseases, such as primary biliary cholangitis (PBC)." (PMID 32784743, 2020).
prostate tumors (2 papers, 2020 to 2024). "In Pten-deficient prostate tumors with Klf5KR mutant, overactivation of Fgfr1 signaling was further supported by increased Fgf9 secretion and upregulated Cx3cr1 expression." (PMID 38781024, 2024). "The actions of the CX3CL1/CX3CR1 axis in prostate tumor metastasis are mediated via induction of EMT and promotion of cell migration." (PMID 32585812, 2020). "Human prostate tumors express CX3CR1, which facilitates their adhesion to bone marrow CX3CL1-expressing endothelial cells as well as osteoblasts, and triggers PI3K/AKT pathway activation." (PMID 32585812, 2020).
renal carcinoma (2 papers, 2021 to 2023). A carcinoma arising from the epithelium of the renal parenchyma or the renal pelvis. "Currently, CX3CR1 is expressed on the membranes of natural killer cells (NK cells), tubular cells, mast cells, platelets, dendritic cells (DCs), effector T cells, renal cancer cells, vascular smooth cells, mesenchymal cells, and monocytes/macrophages." (PMID 36969169, 2023).
renal cell carcinoma (2 papers, 2023). "Tsaur and his colleagues demonstrated that renal cells carcinoma of the chromophobe subtype had considerably reduced CX3CL1 gene expression relative to normal tissue, and that CX3CR1 and C-reactive protein were positively correlated." (PMID 37153002, 2023).
Respiratory Syncytial Virus Infection (2 papers, 2023 to 2024). "CX3CR1 is also a major receptor for respiratory syncytial virus infections and has been found to modulate airway inflammation and mucus production, as well as LPS-induced lung injury through NFκB activation." (PMID 38481391, 2023).
retinal (2 papers, 2011 to 2012). "Previous studies have shown that mice with deletions of certain chemokine such as ccl2 or chemokine receptors including ccr2 or cx3cr1 or both ccl2/cx3cr1 genes develop retinal lesions akin to human AMD." (PMID 21850237, 2011). "We concluded that intravitreous administration of recombinant TSG-6 might stabilize retinal lesions in Ccl2-/-/Cx3cr1-/- mice on rd8 background." (PMID 22452753, 2012).
Rett syndrome (2 papers, 2019 to 2023). A severe neurodevelopmental disorder affecting the central nervous system. "Moreover, in a mouse model of Rett syndrome, it was shown that the presence of CX3CR1 is detrimental to the neurodevelopmental trajectory and (partial) ablation of CX3CR1 attenuated disease severity." (PMID 36674940, 2023).
scrapie (2 papers, 2014 to 2016). A fatal disease of the nervous system in sheep and goats, characterized by pruritus, debility, and locomotor incoordination. "Initially we quantified the amount of detectable gliosis in the thalamus of preclinical scrapie-infected mice, using Gfap and Vimentin as markers of astroglia, and Gpr84 and Cx3cr1, as markers of microglia." (PMID 27046083, 2016).
septic shock (2 papers, 2016 to 2020). Shock caused by infection; frequently caused by gram negative bacteria, although some cases have been caused by other bacteria, viruses, fungi, and protozoa; characterized by fever, chills, tachycardia, tachypnea, and hypotension. "In septic shock patients (n = 279), similar associations were observed between decreased D1 CX3CR1 mRNA expression and D7 mortality (AUC 0.69, aOR 2.76, 95 % CI 1.32–5.75) as well as decreased D3 expression and D28 mortality (AUC 0.72, aOR 3.98, 95 % CI 1.72–9.23)." (PMID 27364780, 2016).
Splenomegaly (2 papers, 2022 to 2023). Abnormal increased size of the spleen. "acted synergistically to attenuate splenomegaly and renal lymphadenopathy through secreted factors and a CX3CR1-dependent mechanism." (PMID 35967418, 2022). "attenuate splenomegaly and renal lymphadenopathy through secreted factors and a CX3CR1-dependent mechanism." (PMID 35967418, 2022). "attenuated splenomegaly and renal lymphadenopathy via a CX3CR1-dependent mechanism, suggesting that CX3CR1 may be used as a target for therapeutics." (PMID 38299151, 2023). "attenuated splenomegaly and lymphadenopathy through secreted factors and a CX3CR1-dependent manner." (PMID 35967418, 2022).
uremia (2 papers, 2018 to 2022). A clinical syndrome associated with the retention of renal waste products or uremic toxins in the blood. "Uremia may also drive monocytic CX3CR1 expression–the fractalkine receptor facilitates adhesion to the endothelium–with consequences for monocyte homing, as demonstrated in a small study examining blood monocytes from patients receiving renal hemodialysis." (PMID 35896846, 2022). "Although proinflammatory Mo2 and Mo3 monocytes are upregulated in hemodialysis patients, decreased expression of CX3CR1 on these cells may contribute to the uremia-related impaired immune response." (PMID 30228352, 2018). "Moreover, our results indicate that especially monocytic CX3CR1 expression is heavily impacted by uremic conditions and might be best suited as biomarker for distinguishing between changes due to uremia and dialysis procedures." (PMID 30228352, 2018).